LEP (leptin)
Diseases named in the same sentence as LEP in open-access papers (continued):
Sharing a sentence is not in itself a finding about the gene and the disease.
infection (continued). "In addition, the levels of one biomarker, leptin, were lower in the post-infection compared to pre-infection specimens." (PMID 37461626, 2023). "Because the ratio of adiponectin and leptin have been proposed as a marker of adipose tissue dysfunction, we enumerated the adiponectin/leptin ratio and detected a significant induction of the adiponectin/leptin ratio in serum of T. spiralis-infected mice at 7 and 14 days post-infection." (PMID 37635188, 2023). "Importantly, Adv36 infection leads to the decreased production of the proinflammatory, immunoregulatory adipokine leptin, and the increased production of the anti-inflammatory adipokine adiponectin." (PMID 36936928, 2023). "However, this is not achievable for many individuals and the findings of our study open up the potential for leptin manipulation or IFN administration as novel strategies for conferring protection from severe infections." (PMID 37857661, 2023). "Another possible explanation for this apparent discrepancy is that insulin resistance, leptin resistance and/or other aspects of the metabolic syndrome may perturb the infection/adipogenesis/cathelicidin pathway identified by Zhang and colleagues." (PMID 36936928, 2023). "Because T. spiralis larvae initiates infection by penetrating the epithelium of the small intestine, we further evaluated the expression of adiponectin and leptin in the jejunum of mice infected with T. spiralis at different time points using quantitative real-time PCR analysis." (PMID 37635188, 2023). "Whether the observed infection-mediated appetite suppression is directly linked to elevated rainbow trout GDF-15 and/or leptin levels in this model requires further study." (PMID 37928534, 2023). "Furthermore, we analyzed the changes of 22 common metabolites in zebrafish and mice in response to infection in the leptin mutant compared with the WT controls." (PMID 35933481, 2022). "Future experiments could be designed to test the hypothesis that leptin is increasing the pro-inflammatory immune response to resist infection, reduce necrosis, and prevent uncontrolled bacterial growth in the skin." (PMID 36093099, 2022). "Furthermore, the infection generates a reduction in the synthesis and secretion of leptin of up to 52%, the accumulation and de novo synthesis of fatty acids, and an increase in glucose uptake of up to 93%." (PMID 35682832, 2022). "All animals were female and none were lost due to infection, removing both estrogen and bacterial lipopolysaccharide as potential causes of increased leptin expression." (PMID 35721743, 2022). "Adipokines like adiponectin and leptin also increased in the infection-primed group." (PMID 36119038, 2022). "We only see very few metabolites, namely trimethylamine N-oxide, mannose in zebrafish larvae and 3-aminoisobutyric acid and putrescine in mice of which the levels are changed more severely in the leptin mutant in the presence of infection as compared to the WT." (PMID 35933481, 2022). "However, in the absence of a blood glucose concentration analysis, it is also difficult to see how the effect of leptin on insulin concentration affected glucose and the potential hyperglycemic state in an acute state of infection." (PMID 35897684, 2022). "In addition, in local infection sites, where the tissue contains several adipocytes that produce leptin, phagocytic activity appears up-regulated, and neutrophils are stimulated by leptin to secrete reactive oxygen species." (PMID 35214179, 2022). "Females have higher leptin during the whole course of infection (1–39 days)." (PMID 35762936, 2022). "For example, leptin levels of the obese mice were already strongly elevated before the infection." (PMID 35406000, 2022). "Moreover, treatment of obese mice with anti-leptin-antibodies resulted in improved survival and downregulated cytokine levels, emphasizing again the role of leptin in obese mice during the course of infection." (PMID 33810619, 2021).
infection (continued). "Therefore, it seems that, upon infection, subjects with fat mass excess are prone to produce more leptin which in turn activates monocytes promoting a positive feedback loop and severe cytokine storms." (PMID 33804765, 2021). "The random selection of the study participants, the use of standardized anthropometrical and laboratory measurements, and the exclusion of participants with extreme values of leptin and inflammatory markers/indications of infection enhanced the quality of the data used and the statistical analyses." (PMID 33680494, 2021). "Leptin, an adipocyte-derived hormone/cytokine, is expressed during inflammation and infection." (PMID 33671172, 2021). "However, there is also evidence supporting a differing role of leptin signaling during infection of obese mice’s lungs." (PMID 33810619, 2021). "The roles of insulin and leptin in central nervous system (CNS) infection." (PMID 34795562, 2021). "In obese patients with a viral infection, altered leptin sensitivity may contribute to a dramatic pro-inflammatory cytokine response and to an inefficient response to infection." (PMID 35002761, 2021). "Upon infection, patients with excessive fat mass would be prone to produce more leptin." (PMID 35002761, 2021). "During human infection, food intake will decrease with a change in leptin synthesis, and this will probably reduce the ingestion of other pathogens, activate energy-requiring mechanisms and diminish the competition of epitopes from nutrients for crucial receptors for pathogen sensing." (PMID 33732247, 2021). "Similarly, others have reported that rats infected with the closely related parasite T. gondii presented higher plasma leptin levels 4 weeks after infection." (PMID 32709166, 2020). "Having determined that N. caninum infection influenced leptin mRNA levels, we assessed whether transcription of the leptin receptor could also be influenced by infection." (PMID 32709166, 2020). "This decrease in serum levels could, however, result from the observed decrease in leptin mRNA levels in the adipocyte fraction upon infection since adipocytes are the main source of circulating leptin." (PMID 32709166, 2020). "The level of leptin typically become increased during infection and inflammation, and it has been shown in mice that starvation may prevent this increase in leptin and attenuate symptoms of autoimmune reactions." (PMID 33304252, 2020). "Moreover, leptin stimulates chemotactic activity and function of neutrophils by enhancing production of oxygen species crucial for host cell defense against infections, and by promoting an anti-apoptotic cellular response." (PMID 32655492, 2020). "DIO mice possess of higher leptin level than the lean mice before and after infection, which suggested that the pulmonary apoptosis mediated by ER stress could be suppressed by leptin." (PMID 32685099, 2020). "In other infection models, however, leptin has been attributed host-protective effects." (PMID 32709166, 2020). "In the current study, after infection, the level of leptin was significantly increased in DIO-E." (PMID 32104715, 2020). "Importantly, infection was associated with depot-specific modifications in WAT’s lipid metabolism and leptin secretion." (PMID 32409640, 2020). "However, at 24 h post-infection, levels of LEP and CTSL were up-regulated (~ 2.1-fold and ~ 1.4-fold respectively)." (PMID 32275661, 2020). "Acute leptin during infection and inflammation may be a protective module of the host response to inflammation." (PMID 29868503, 2018). "In Uganda, circulating leptin, a marker of white adipose tissue that is associated with energy production during infection and long-term mortality, did not change significantly after hospital discharge." (PMID 29635501, 2018). "Moreover, leptin also affects other physiological functions, namely bone metabolism, inflammation, infection and immune responses." (PMID 29910742, 2018).
infection (continued). "K. pneumonia infection has amplified the mortality rate in leptin-deficient mice by impairing bacterial clearance, and an in vitro study demonstrated that leptin supplementation reduced this infection by increasing the phagocytic activity of alveolar macrophages." (PMID 29868503, 2018). "Leptin (adipocyte derived cytokine) is considered as a central mediator between nutrition, neuroendocrine system and immunity and PMN has been reported to result in a decreased concentration of leptin, thus increasing the susceptibility to infection." (PMID 30618587, 2018). "Indeed, in in vitro assay utilizing isolated macrophages, addition of leptin increased the production of proinflammatory cytokines following infection with F. tularensis." (PMID 30046592, 2018). "In the small intestine, leptin modulates the absorption of sugars and peptides, while in the hindgut leptin may inhibit infection." (PMID 27998953, 2017). "Subsequently, infection induced low plasma leptin could facilitate an impaired T-cell response as reported in tuberculosis." (PMID 29116252, 2017). "Leptin alterations in the acute phase of infection had been already reported by other authors." (PMID 26921251, 2016). "Therefore, particularly, TNF-alpha, interleukin-1 (IL-1), and IL-6 are considered to be responsible for inflammation and anorexia occurring during infection and leptin is considered to partially mediate these effects of cytokines." (PMID 26697061, 2015). "Decreased leptin levels in patients with complicated infection may contribute to poor clinical outcome by reducing the host's ability to eradicate the infection." (PMID 25398383, 2014). "Infection with N. brasiliensis, however, significantly decreased leptin expression." (PMID 24465430, 2014). "For example, leptin has been reported to play an important role in the activation of regulatory T cells during immunization and we observed reduced numbers of NK cells in db/db mice following infection with the influenza A virus." (PMID 25232724, 2014). "Moreover, via maintaining naive levels of the adipose secreted hormone leptin throughout infection we demonstrate a novel feedback loop in the immunoendocrine axis." (PMID 23349631, 2013). "However, our data demonstrate that brief alterations in leptin can benefit immunity in terms of Th2 driven resistance to infection." (PMID 23349631, 2013). "Leptin levels normally increase acutely during infection and inflammation." (PMID 21695035, 2011). "As most placentally-derived leptin is released into the maternal circulation, we postulate that PM infection may reduce the release of leptin into the maternal circulation." (PMID 22174834, 2011). "Infection has been shown to increase serum leptin levels in vivo." (PMID 21695035, 2011). "In this context, leptin levels increase acutely during infection and inflammation, and may represent a protective component of the host response to inflammation." (PMID 20368778, 2010). "Interestingly, this group of genes also included leptin (LEP), alluding to a link between infection and energy partitioning in the form of lipid storage and metabolism." (PMID 18513449, 2008). "Moreover, circulating leptin levels also increase in acute inflammation and infection." (PMID 37217748, 2023). "However, exogenous administration of leptin induced Th1 polarization, diminished Th2 response, controlled parasite growth in visceral organs, and induced hepatic granulomatous response to clear the infection." (PMID 36985226, 2023). "This might be because leptin mutant zebrafish embryos have a different yolk composition that favors mycobacterial growth or an indirect metabolic systemic effect of this that could influence later stages of infection." (PMID 35933481, 2022). "Furthermore, a growing body of evidence suggests that leptin can also regulate immune function (especially T lymphocyte function) and may be involved in the response to infection." (PMID 35011102, 2022).
infection (continued). "Elevated BMI might interfere with the individual’s ability to mount an effective immune response to vaccination or infection, due to high levels of body fat and the increased production of leptin—a pro-inflammatory hormone with important immunological functions." (PMID 36016129, 2022). "In addition, infection upregulates leptin signaling and inhibits insulin signaling." (PMID 34768822, 2021). "It remains to be determined whether the infection by respiratory viruses affects leptin levels." (PMID 32133330, 2020). "CRP and leptin but not IL-6 were significantly higher in the Ob group regardless of any underlying health condition, the progress of pregnancy, or the presence of any complication or infection." (PMID 30909605, 2019). "Indeed, IL-2R and sIL-6Ra show a significant correlation with the fibrotic stage of our CHC patients, as well the elevated levels of leptin indicate that immune response and host defense, active during infection and inflammation, are acting as paracrine modulator of the hepatic fibrogenesis." (PMID 26226632, 2015). "Leptin secreted by adipocytes sustains Th1 responses by promoting Teff cell proliferation and pro-inflammatory cytokine production and by constraining Treg cells expansion: this balance between Teff and Treg cells leads to immune tolerance on one side and to protection from infections on the other." (PMID 25601869, 2014). "Adipocyte hypertrophy is linked to an enhanced inflammatory profile.In line with this our findings show that both HIV tropisms increase the LEPTIN/ADIPONECTIN ratio and stimulate IL-1β secretion at 10 days post-infection." (PMID 40746960, 2025). "Although leptin does not trigger calcium mobilization, ROS generation, or β2-integrin upregulation, its capacity to desensitize neutrophils may underlie the heightened susceptibility to infection observed in hyperleptinemic states such as ESRD." (PMID 41516046, 2025). "Leptin upregulates ROS production and inhibits the migration of the neutrophils.Leptin can increase the expression of inflammatory factors (IL-2, IL-12, and IFN-γ) in monocytes to induce a Th1-dominant immune response in infection." (PMID 39220365, 2024). "The decrease in leptin, a marker of energy expenditure, is consistent with previous studies finding lower leptin in ART-treated PWH, likely due to HIV-infection-induced catabolism." (PMID 37461626, 2023). "Multiple biomarkers, including IP-10, IL-6, sCD163, leptin, IL-8, and LBP were variable either within each participant’s two pre-infection or two post-ART-suppression specimens." (PMID 37461626, 2023). "Outliers with elevated biomarkers observed in both pre-infection specimens included IL-1β (N=1 participant), suPAR (N=2), MCP-1/CCL2, sCD163, and CRP (N=3), TNFα (N=9) and/or leptin (N=23)." (PMID 37461626, 2023). "Therefore, preventive measures should include not only vaccination and the well-established actions intended to avoid infection, but also the appropriate dietary and lifestyle interventions aimed at improving body composition and preventing or even reversing metaflammation and leptin resistance." (PMID 35406000, 2022). "However, these phenomena might have been related to metabolic and nutritional impairments caused by the infection, and so did not suggest that the leptin level is predictive of the occurrence of infections." (PMID 35011102, 2022). "Leptin facilitates Th17 cells, which are a CD4+ proinflammatory T-cell subset generated to hinder infections, such that LepR on T-cell membrane is required for full Th17 differentiation." (PMID 33804765, 2021). "The top predicted transcriptional regulators (P < .01) at 2 h post-infection were wortmannin, CSF3 which is predicted to be activated, LEP, JNK, and, IL5 which are predicted to be inhibited." (PMID 33382951, 2021). "The expression of LEP and CTSB remained unchanged at 6 h post-infection, whereas CTSL showed down-regulation, which is in agreement with earlier reports." (PMID 32275661, 2020).
infection (continued). "After infection, when compared with the lean group, the contents of TNF-α, IL-1β, IL-6, IL-8, resistin, and leptin in the lean-E." (PMID 31085802, 2019). "Before infection with E. coli, TNF-α, IL-6, resistin, and leptin contents of the DIO group were significantly higher (p<0.05) than those of the lean group." (PMID 31085802, 2019). "Before infection with E. coli, the DIO groups had significantly higher contents of IL-6, leptin, and resistin but lower content of IL-8 compared with the lean groups (p < 0.05)." (PMID 30250258, 2018). "Based on our results, the DIO mice showed higher MDA contents, GSH-Px activity, and adipocytokine (leptin, resistin, and IL-6) levels than the lean mice, indicating that DIO mice suffered from high oxidative stress levels before infection." (PMID 30250258, 2018). "Circulating leptin levels are increased in animals fed a HFD and in animal with inflammation and/or infection states and it affect cytokine production." (PMID 26891322, 2016). "In this study, we identified several proteins (FABP4, LEP, RARRES2, MSTN, C2, SELE and IL6) that belong to a family of chronic pro-inflammatory cytokines and are primarily produced in response to infection or stress, some of which are mainly produced by adipose tissue (FABP4, LEP and RARRES2)." (PMID 38548792, 2024). "However, we found that multiple biomarkers, including IP-10, IL-6, sCD163, leptin, IL-8, and LBP, were significantly changed in the same direction across participants, either within each participant’s two pre-infection or two post-ART-suppression specimens." (PMID 38976697, 2024). "We performed immunophenotyping eight days after infection and found a marked increase in both the spleen size and number of CD45+ cells in ob-leptin mice, including an increase in the proportion of B cells and a concomitant decrease in the proportion of T cell receptor β (TCRβ+) cells." (PMID 39480494, 2024). "Following infection for 7 days, the mRNA expression of adiponectin, but not leptin, was significantly induced." (PMID 37635188, 2023). "Cord blood leptin was unaltered in the presence of clinically diagnosed infection but correlated with IL-6 in the absence of infection." (PMID 35197933, 2022). "By linear regression, cord blood IL-6 in those without suspected infection was significantly correlated with cord blood leptin (N=79, R=0.39, P<0.001) but not insulin (R=0.10, P=0.37)." (PMID 35197933, 2022). "There were four metabolites of which the level was no longer significantly changed in the leptin mutant after infection in both zebrafish larvae and mice." (PMID 35933481, 2022). "Incubation of endothelial cells with the pro-inflammatory AT-derived mediator, leptin, prior to virus inoculation, did not alter the expression of endothelial SARS-CoV-2 entry receptors and did not alter their susceptibility to infection." (PMID 35837388, 2022). "Leptin-based therapies have the potential to expedite healing and reduce the incidence of secondary infections without toxicity issues, the threat of antibiotic resistance, or environmental antibiotic contamination." (PMID 36093099, 2022). "Additionally, the top predicted transcriptional regulators (P < .01) at 2 h post-infection of the pre-treated cells were dextran sulfate, TLR4, kinase EIF2AK3, FCGR2A, and LEP." (PMID 33382951, 2021). "Leptin promotes the differentiation and function of both human and mouse TFH cells in culture and is required to support TFH function and effective humoral immunity to infection, immunisation and vaccination in mice." (PMID 34031386, 2021). "The absence of leptin triggers the immune defects that eventually translate into exaggerated death due to infections." (PMID 34220807, 2021). "This Th1 inducer increases with Mtb infection and mice lacking leptin have higher BL in advanced stages of infection." (PMID 33936040, 2021). "Not exclusively adipose and immune cells produce leptin in the context of the inflammatory response upon infection." (PMID 33804765, 2021).